ZNF48 (zinc finger protein 48)
Description:
May be involved in transcriptional regulation.
Synonyms: ZNF553; DKFZp762K013; FLJ31751; MGC43952
Tractability: PROTAC: UniProt records ubiquitination sites on it; ubiquitination databases record sites on it.
Gene: Protein-coding gene on chromosome 16 (30,378,106 to 30,400,108, forward strand). Ensembl gene ENSG00000180035.
Subcellular location: Nucleus
Subcellular location (Human Protein Atlas): Mitochondria
Gene Ontology:
Molecular function: identical protein binding; protein binding; transcription cis-regulatory region binding
Biological process: regulation of transcription by RNA polymerase II
Cellular component: nucleus
Genetic constraint (gnomAD): Loss-of-function variants: 20 observed, 38.04 expected, observed/expected ratio (o/e) 0.53, 90% interval 0.37 to 0.76. The upper end of that interval is the gene's LOEUF score, 0.76, which puts it in group 3 of 6, group 1 being the genes least tolerant of losing a copy. Missense variants: 726 observed, 867.7 expected, observed/expected ratio (o/e) 0.84, 90% interval 0.79 to 0.89. Synonymous variants: 298 observed, 335.32 expected, observed/expected ratio (o/e) 0.89, 90% interval 0.81 to 0.98.
Homologues: Orthologues: chimpanzee ZNF48 (99% identical), macaque ZNF48 (99% identical), pig ZNF48 (95% identical), dog ZNF48 (95% identical), rabbit ZNF48 (91% identical), guinea pig ZNF48 (87% identical), rat Znf48 (85% identical), mouse Zfp553 (83% identical), zebrafish znf646 (22% identical), zebrafish si:dkey-89b17.4 (21% identical), zebrafish znf576.1 (16% identical), Drosophila melanogaster CG1602 (14% identical), and 7 more. Paralogues in human: ZNF91 (30% identical), ZNF84 (29% identical), ZNF594 (28% identical), ZNF184 (28% identical), ZNF160 (28% identical), ZNF99 (28% identical), ZNF420 (27% identical), ZNF497 (27% identical), ZNF107 (27% identical), ZNF665 (27% identical), ZNF208 (27% identical), ZNF473 (27% identical), and 24 more.
Diseases named in the same sentence as ZNF48 in open-access papers:
ZNF48 is named in the same sentence as 4 diseases in open-access papers, as found by Europe PMC text mining. Sharing a sentence is not in itself a finding about the gene and the disease. The quoted sentences say what the papers report.
myopia (1 paper, 2024). "With the comparisons of positive rates of each autoantibody between emmetropia and high myopia groups, a total of 18 autoantibodies, including anti-ZNF48, anti-HSPA1L, etc. were identified as high myopia-related candidate autoantibodies (Fisher’s exact test, all p < 0.05)." (PMID 38729610, 2024).
ZNF48 also shares sentences with these, for which no sentence is quoted: mood disorder (1 paper); psychosis (1); schizophrenia (1).